INS (insulin)
Diseases named in the same sentence as INS in open-access papers (continued):
Sharing a sentence is not in itself a finding about the gene and the disease.
cancer (continued). "Noteworthy, cancer cells overexpress the isoform A of IR (IR-A), which is predominantly expressed in embryo and fetal tissues, where it contributes to insulin and IGF-II mediated growth and development." (PMID 24115945, 2013). "There has been a steady increase in the interest in the importance of insulin and the insulin receptor in cancer progression." (PMID 23983688, 2013). "Insulin/IGF-I signaling pathways have been widely implicated in the processs of tumor development and progression of different types of cancer being considered an important target with promising therapeutic aplications in cancer." (PMID 24282611, 2013). "Suppression of PKM2 activity presents yet another dimension of insulin’s role in promotion of cancer metabolism." (PMID 23837608, 2013). "One possible explanation for the molecular mechanisms of BCAAs to prevent cancer incidence was reported, in which BCAAs inhibited insulin-induced hepatic tumor cell proliferation by inducing apoptosis through the activities of mTORC1 and mTORC2." (PMID 24223226, 2013). "Various mechanisms have been associated with several cancers, such as alterations in sex hormones and insulin growth factors, immune modulation, alterations in free radical generation, factors affecting body fat distribution, and direct effects on cancer." (PMID 23776686, 2013). "An effect of metformin reducing cancer progression would therefore be entirely consistent with all of the evidence regarding metabolism and the effects of insulin and IGFs on cancer progression." (PMID 23907184, 2013). "The influence of miRNAs on the expression of insulin system mRNAs is not only limited to muscle cells and differentiation but also extends to cancer cells since IGF and IGFR are crucial for tumor growth." (PMID 24051403, 2013). "It is activated by insulin, glucocorticoids, tumor necrosis factor-alpha (TNFα), and estrogens and induces cancer progression by activation of the JAK2/STAT3, PI3K, and MAPK pathways through LEPR-B." (PMID 23819063, 2013). "Both GI, and in particular GL, have been suggested to be relevant factors in the cancer incidence due to the potential role of insulin and insulin grow factor (IGF) in cancer promotion." (PMID 24267672, 2013). "Nevertheless, a crucial role is supposed to be played by the altered insulin signaling, occurring in obese/overweight patients, which fuels cancer cell growth, proliferation and survival." (PMID 23981814, 2013). "Stimulation of cancer cells with insulin and IGF-I growth factors led to a significant upregulation of the fibronectin mesenchymal marker, and an alteration of E-cadherin and β-catenin cellular localization." (PMID 24282611, 2013). "Here we provide new insights into the role that Insulin/IGF-I signaling play during cancer progression through glycosylation modifications." (PMID 24282611, 2013). "At the same time, clinical trials show that the effect of insulin therapy on the incidence of cancer, if present at all, is certainly smaller than that suggested by epidemiological studies." (PMID 23209929, 2012). "IR-A, which appears to mediate growth-stimulating effects more than metabolic actions of insulin, is overexpressed in many cancer cells; this is one of the reasons of the hypersensitivity of malignant cells to the growth-promoting effects of insulin." (PMID 23209929, 2012). "Cancer mortality is about doubled among insulin users relative to metformin users (HR = 1.9; 95% CI: 1.5–2.4)." (PMID 22778714, 2012). "Based on the considerations expressed above, it is very likely that observational studies overestimate the effect of insulin therapy on the incidence of cancer." (PMID 23209929, 2012). "In a study of 10309 diabetics, cancer related mortality was reported in 3.5% of metformin users, 5.9% of sufonylurea users, and 5.8% of insulin users." (PMID 22978440, 2012).
cancer (continued). "The extended followup if the trial (median 4.1 year) revealed that patients randomized to chronic insulin treatment (group 1) has a significantly higher (4.4 versus 2.0%) cumulative cancer-related mortality than the other two groups." (PMID 23209929, 2012). "Even if this tissue appears as normal prostate tissue histologically, its composition of insulin signaling molecules is more similar to cancer than to healthy tissue." (PMID 23251408, 2012). "Up-regulation of insulin signaling in liver and adipose tissues increases steatosis and fat mass, respectively and the same pathway supports growth and chemo-resistance of cancer cells." (PMID 23056418, 2012). "Unfortunately, very few studies report analyses performed with the exclusion of early cases of cancer (diagnosed in the first few months after the initiation of insulin therapy)." (PMID 23209929, 2012). "This comment analyzes enzymatic switches regulated by insulin after a meal or after fasting and discusses their potential in cancer in particular." (PMID 22954255, 2012). "In vitro, insulin stimulates the growth of cancer cells, through the interaction with insulin-like growth factor-1 (IGF-1) receptors and its own receptors." (PMID 23209929, 2012). "PIK3R1 is a regulatory subunit of the phosphoinositide-3-kinase, which is a protein known to be involved in insulin actions, cancer signaling, and cytokine signaling." (PMID 23281828, 2012). "FOXO transcription factors are highly conserved genetic pathways, at the intersection of aging and cancer, that are phosphorylated in response to insulin and growth factors." (PMID 22916126, 2012). "Cancer thyrosphere growth was stimulated by insulin and IGFs, while IGF-II was most potent in inducing cell renewal." (PMID 22927847, 2012). "This review focuses on miRNA regulations of cancer cell metabolism,including glucose uptake, glycolysis, tricarboxylic acid cycle and insulin production, lipid metabolism and amino acid biogenesis, as well as several oncogenic signaling pathways." (PMID 23164426, 2012). "Reduced insulin and IGF-1 signaling has been associated with animal and human longevity.On the other hand, inhibition of insulin/IGF-1 signaling is one anti-cancer strategy under intensive investigation." (PMID 23455653, 2012). "In this respect, PTEN is often disrupted in tumour cells, and this emphasizes the role of the insulin/IGF-I-induced PI3K/Akt/mTOR/S6K signaling in cancer." (PMID 22701472, 2012). "It is possible that insulin therapy has a greater detrimental effect on mortality to a greater extent than incidence of cancer." (PMID 23209929, 2012). "GSK3β is known to be involved in multiple pivotal signaling pathways and has been shown to play a role in development, cell polarity, insulin signaling, metabolic regulation, neurodegenerative disorders, and cancer." (PMID 23166798, 2012). "On the other hand interferon α which are reported to have antibreast cancer activities through the “cross talk” between the receptors of insulin, estrogen and progesterone." (PMID 23675265, 2012). "The investigated cell lines are widely used in cancer research and are well characterized in the context of their metabolic response to increased availability of glucose and insulin." (PMID 22554284, 2012). "Activation of the PIP3-AKT pathway via stimulation received by growth factors and insulin is a common event in several cancers, and leads to the activation and translocation of phosphorylated AKT into the cytoplasm." (PMID 22489133, 2012). "In this analysis, we followed all studied insulin users to the earliest of cancer diagnosis, death, disenrollment, discontinuing studied insulin or switching to another insulin, or study end." (PMID 21738645, 2011). "Some epidemiological studies demonstratea direct correlation between insulin and C-peptide levels and cancer development,especially in obese individuals." (PMID 23908801, 2011).
cancer (continued). "In contrast, adiponectin is of particular interest for cancer prevention because of its unique metabolic properties which include the ability to decrease hepatic gluconeogenesis, to increase insulin sensitivity, and to reduce adipogenic inflammation." (PMID 21773024, 2011). "It has important roles in maintaining insulin sensitivity in adipocytes and cell growth in cancer cells." (PMID 21119656, 2011). "Hazard ratio of overall and individual cancer comparing exclusive use of insulin glargine with intermediate/long-acting human insulin (HI) among men and women." (PMID 21738645, 2011). "Hazard ratio of overall and individual cancer comparing exclusive users of insulin glargine vs. intermediate/long-acting human insulin (HI) using age as timescale in the Cox proportional hazard model." (PMID 21738645, 2011). "The main support for such a possibility comes from studies conducted on human cancer tissue specimens and revealing the presence of intratumoral insulin." (PMID 21457557, 2011). "Evidence suggests a direct link between serum insulin and elevated blood glucose levels and several cancer sites." (PMID 21738645, 2011). "Crude incidence rate of any cancer and individual site of cancer among exclusive users of insulin glargine vs. intermediate/long-acting human insulin (HI)." (PMID 21738645, 2011). "Pathways involved in cancer, Wnt signaling, and insulin-signaling pathways were among the most significant." (PMID 21731631, 2011). "Several studies have demonstrated the increased likelihood of developing cancer in patients treated with insulin or insulin secretagogues as compared with Metformin." (PMID 21668983, 2011). "GH, IGF-1 and insulin have cancer-promoting actions and raised serum IGF-1 levels have been associated with increased risk of prostate, breast and colorectal cancers." (PMID 21699736, 2011). "Hazard ratio of overall and individual cancer among exclusive users of insulin glargine vs. intermediate/long-acting human insulin (HI) users." (PMID 21738645, 2011). "Epidemiological studies are hampered by the heterogeneity of diabetic patients with respect to their degree of glycaemic control which will influence their circulating insulin levels and hence making correlations with cancer development difficult." (PMID 21696633, 2011). "Second, mTOR overactivation can cause insulin resistance, which in turn leads to a compensatory increase in insulin levels, which can promote cancer." (PMID 22267462, 2011). "Exclusive users were followed from the date of insulin initiation to the earliest of cancer diagnosis, death, disenrollment, or December 31 2007." (PMID 21738645, 2011). "This article provides new insights into the modulation of cancer cell adhesion and migration processes by diabetogenic glucose and insulin concentrations." (PMID 21179032, 2011). "It has been proposed that the IGF system mediates the effect of hyperinsulinaemia and is more relevant to cancer development and progression than insulin." (PMID 21696633, 2011). "Despite this design allowed us to estimate the incidence of cancer following a new episode of insulin treatment, follow-up duration was substantially shorter as compared with analysis on exclusive users which led to imprecise risk estimates." (PMID 21738645, 2011). "A potential mechanism for such intracellular insulin-driven tumor growth is the insulin-RB complex formation that, so far, has been experimentally demonstrated in several human carcinoma-derived cell lines." (PMID 21457557, 2011). "Cumulative evidence has been obtained concerning the role of the IGF/INS network in the emergence and progression of cancer." (PMID 20924377, 2010). "Since the previous International Workshops on Insulin and Cancer held in Düsseldorf/Germany in 2007 and in 2008, considerable progress in the study of the issue has been noticeable." (PMID 21176129, 2010).
cancer (continued). "Unfortunately, we also found constant and reproducible development of NPC derived cancer mainly sustained by the insulin secretion." (PMID 20436918, 2010). "Taken together, considerable progress in the study of the Insulin-Cancer-Connection was noted, making a continuation of the International Workshops on Insulin & Cancer desirable." (PMID 21176129, 2010). "Unfortunately, stable graft function was accompanied by constant and reproducible development of NPC-derived cancer mainly sustained by insulin secretion." (PMID 20436918, 2010). "IGF-II is a mitogenic polypeptide related to insulin and thought to serve as a growth factor in various cancers through coexpressing IGF-II and IGF-I receptors, which is a kind of fetal growth factor and highly expressed during hepatocarcinogenesis." (PMID 24281095, 2010). "Epigenetic, expression and protein analyses have demonstrated alterations of IGF/INS expression and protein levels in cancer tissues." (PMID 20924377, 2010). "More recently, it has also become evident that high circulating levels of insulin are an important factor of cancer promotion." (PMID 19609453, 2009). "Several growth factor/hormone signaling pathways that are associated with cancer including fibroblast growth factor (FGF), epidermal growth factor (EGF) and insulin can modulate IRS-1 and IRS-2 expression levels." (PMID 19534786, 2009). "Although PPARγ plays an important part in the transmission of insulin responses andphysiological diet, little direct evidence exists relating these factors toPPARγ activation and the risks of thedevelopment of cancer." (PMID 18596912, 2008). "In particular, toxin compounds mentioned in this review are reported to be cancer promoter or toxic in cellular or organic systems and mainly known as a blocker of insulin effects." (PMID 19330070, 2008). "Over the 4 h feeding period, insulin concentrations increased significantly both in the control (P=0.006) and cancer groups (P<0.001)." (PMID 15026790, 2004). "Blood insulin in patients with ES tumours was four times higher than the control value in cancer-free subjects, but fell to normal levels at AS and after ES surgery (PES)." (PMID 7981074, 1994). "In contrast, surgery was associated with a substantially lower rate of mortality from female-specific cancers in the highest insulin third (HRadj = 0.37; 95% CI [0.16, 0.85]; p = 0.019), with evidence of heterogeneity by insulin level (adjusted treatment–insulin interaction p = 0.039)." (PMID 41490246, 2026). "We then examined IRs of female-specific cancers across insulin subgroups." (PMID 41490246, 2026). "Additionally, given the potential adverse impact of insulin on cancer survival outcomes, there is a compelling rationale for early intervention with non‐insulin antihyperglycemic agents and the integration of endocrinology support within oncology care." (PMID 41287203, 2026). "Patients requiring insulin typically have longer disease duration, more advanced or poorly controlled T2DM, and a greater burden of comorbidities, all of which independently are associated with increased liver disease and cancer risk." (PMID 41607999, 2026). "Additionally, the greater metabolic plasticity observed in polyp-free individuals enables high-MQI diets to optimize insulin sensitivity and lipid metabolism more efficiently, thereby strengthening the cancer-preventive effects." (PMID 41601909, 2026). "Of particular relevance, insulin and estrogen interact in ways that may promote cancer development and progression, including reciprocal receptor activation leading to an increased fraction of bioactive estrogen." (PMID 41490246, 2026). "We next examined cancer mortality across insulin subgroups in women." (PMID 41490246, 2026). "Monami and associates, in 2011, observed that another compelling argument for continuing metformin therapy among individuals receiving insulin treatment may be a reduced likelihood of cancer." (PMID 40572709, 2025).
cancer (continued). "The role of insulin signaling in cancer has also received much attention." (PMID 39948335, 2025). "Moreover, research has shown that Time-Restricted Feeding (TRF) can impact essential pathways related to cancer progression, such as insulin signaling, inflammation, cellular metabolism, and the enhancement of autophagy." (PMID 39912042, 2025). "Recently, Thr406 was identified as a insulin-responsive site on PanK4 in cultured cancer cells." (PMID 39746949, 2025). "For example, Metformin can reduce glucose and insulin levels in the circulation, thereby lowering the concentrations of two factors, which may promote cancer growth." (PMID 40522309, 2025). "Decreased insulin transmission may consequently diminish the proliferative signals that promote cancer in the liver." (PMID 40439888, 2025). "Since cancer progression can involve the acquisition of stem cell-like features that make tumours more likely to spread to distant organs, more resistant to treatment, and result in poor prognosis, a ‘stemness’ score was calculated for the insulin-expressing cancer cells." (PMID 40438247, 2025). "While high-protein diets could promote muscle protein synthesis, advanced cancer patients often exhibit reduced protein utilization due to metabolic disturbances (e.g., insulin resistance and elevated inflammatory cytokines)." (PMID 41487675, 2025). "This occurs mechanistically through downregulation of insulin gene expression and dysregulation of glycolysis/gluconeogenesis pathways.Cancer cells exhibit metabolic reliance on glycolysis for energy production (the Warburg effect), even under aerobic conditions." (PMID 41219936, 2025). "The decades of research on CR suggest that the reduction in cancer incidence in CR is facilitated by the reduction in glucose, insulin, and IGF-1 levels, which would otherwise stimulate cell growth and proliferation, and the reduction in oxidative stress and inflammation." (PMID 40285503, 2025). "Note that this might not only be the case in cancer patients but also in diabetic patients, in whom ROS and MG have been shown to impair the insulin pathway." (PMID 40558563, 2025). "The enrichment of insulin response processes suggests potential crosstalk between metabolic and proliferative pathways, consistent with the role of insulin signaling in promoting cancer cell survival and growth." (PMID 40654937, 2025). "High insulin levels and over-activation of IGF are associated with the development and progression of certain cancers, such as breast, colon, and prostate cancers, and may promote tumor growth by promoting cell proliferation and inhibiting apoptosis." (PMID 39948335, 2025). "Because insulin signalling is required for retaining glucose intake and glycolysis in peripheral tissues, people with cancer who have reduced insulin sensitivity could have a declined rate of glucose degradation, leading to glucose intolerance." (PMID 40275022, 2025). "The impact of glucose-lowering drugs on cancer risk is still not clear, while associations among insulin, other medications, and comorbid risk have been proposed." (PMID 39996906, 2025). "Moreover, insulin and insulin-like growth factors accelerate cell division while inhibiting apoptosis, thus creating favorable hormonal conditions for cancer development." (PMID 40431387, 2025). "Different Ramadan-based studies performed on healthy individuals showed, overall, a substantial remodeling of the gut microbiota, sometimes associated with a positive impact on glucose level, lipid metabolism, insulin signaling, and anti-cancer serum proteomic signatures." (PMID 39940361, 2025). "Differential lipids in the F vs. C, T vs. C, B vs. C, and H vs. C comparisons were mainly enriched in glycerophospholipid metabolism, sphingolipid signaling pathway, choline metabolism in cancer, retrograde endocannabinoid signaling, insulin resistance, and adipocytokine signaling pathways." (PMID 41157279, 2025).